CXCR4 (C-X-C motif chemokine receptor 4)
Diseases named in the same sentence as CXCR4 in open-access papers (continued):
Sharing a sentence is not in itself a finding about the gene and the disease.
tumor (continued). "In addition, CXCL12/CXCR4 signalling encourages angiogenesis and tissue remodelling, resulting in increased tumour vascularisation and increased potential for metastatic spread." (PMID 41002447, 2025). "The authors further demonstrated that the inhibition of the proliferation and invasion of SUM149 and SUM190 breast cancer cells by RhoC knockdown was via the increase of KAI1 (a tumor metastasis suppressor) and decrease of CXCR4 (a tumor progression promoter) and MMP9." (PMID 40214422, 2025). "CXCR4 inhibition could prevent tumor growth and reduce tumor cell survival by downregulating target genes like CCND133." (PMID 40860200, 2025). "Both tumor cells and tumor-associated fibroblasts have the capacity to secrete CXCL12, which serves to attract tumor cells, immune cells, and vascular endothelial cells that express CXCR4, thereby facilitating their migration toward the tumor site." (PMID 41394878, 2025). "CTPCs are a subset of tumor cells that exit into peripheral blood as a result of the dynamic interactions between the tumor plasma cells and BM microenvironment, the most important being the CXCR4 & CXCL12 interaction." (PMID 40296907, 2025). "MMPs contribute to the sprouting of vascular endothelial cells by degrading the vascular basement membrane and extracellular matrix in the early stages of tumor angiogenesis, and CXCR4/CXCL12 signaling pathway mediates cell migration signals and metastasis processes." (PMID 39965034, 2025). "Additionally, CXCR4 blockade modulates immune cell positioning within the tumor microenvironment, enhancing immune infiltration and improving responses to immunotherapy." (PMID 40552145, 2025). "MIF facilitates the invasion and metastasis of tumor cells by binding to CXCR4." (PMID 40110199, 2025). "Importantly, the histone deacetylase inhibitor vorinostat has been shown to downregulate CXCR4 expression in MF cell lines, suggesting a potential therapeutic approach to modulate chemokine receptor-mediated tumor progression." (PMID 40861461, 2025). "The overexpression of the CXCR4/CXCL12 axis induces metastasis formation in different ways: in the tumor microenvironment (TME), hypoxia and toxins cause an increase in CXCL12 levels, generating the migration of CXCR4-expressing tumor cells." (PMID 40142155, 2025). "Additionally, the use of CXCR4 antagonists further facilitates their accumulation within the tumor region." (PMID 40904706, 2025). "Moreover, CXCL12 is highly expressed in metastatic target organs, such as the bone, liver, and lungs, where it establishes chemotactic gradients to guide CXCR4+ tumor cells to these sites." (PMID 40698080, 2025). "Notably, MMP1-mediated MSCs tumor tropism depends on interaction with extrinsic signaling CXCL12/CXCR4." (PMID 40676710, 2025). "Moreover, hypoxic conditions in TME stimulate tumor aggressiveness driven by CXCR4, due to hypoxia-inducible factor 1 alpha (HIF1α) stabilization of CXCR4 expression and tumor cell survival in nutrient deprivations." (PMID 41383468, 2025). "The HGF/MET pathway is classically recognized as a primary initiator of “invasive growth” and EMT driven by stromal paracrine signaling, whereas the CXCL12/CXCR4 axis predominantly functions as a “chemotactic compass” guiding tumor cell homing to specific organs like the bone and lung." (PMID 41514604, 2025). "Within the tumor immune infiltrate, CXCR4 is mainly expressed by both CD4+ and CD8+ lymphocytes." (PMID 40362664, 2025). "Following in situ tumorigenesis in mice, we administered an CXCR4 inhibitor drug via injection into the prostate, resulting in a significant reduction in tumor size in the treated group compared to the control group, as indicated by fluorescence intensity measurements." (PMID 40698080, 2025).
tumor (continued). "In addition, a statistically significant, weak positive correlation was observed in the different RCC subtypes and kidney specimen with the proliferation marker CXCR4 as well as with the two tumor immune checkpoint molecules HLA-G and LGALS9." (PMID 40699665, 2025). "Compared to the oe‐NC+M2pep‐Cs NPs/Plerixafor group, the mRNA levels of CD80, IL‐1β, and IL‐6 were significantly downregulated, and the mRNA levels of CD206 and IL‐10 were significantly upregulated in the tumor tissues of mice in the oe‐CXCR4+M2pep‐Cs NPs/Plerixafor group." (PMID 40536774, 2025). "In some cases, tumor cells express CXCR4, creating a feedback loop that enhances tumor growth." (PMID 40784879, 2025). "In the first study, a novel PET tracer, [(68Ga)] Ga-CXCR4, enabled precise tumor visualization in treatment-naive patients by emitting β-radiation while at the same time offering future utility for automated tumor delineation via machine learning." (PMID 40806525, 2025). "In addition to its role in tumor growth, CXCR4 is critically involved in tumor metastasis and invasion." (PMID 41149503, 2025). "Thus, high CXCL12 levels in the TME provide paracrine signaling through a feedback loop that mediates integrin b1 accumulation on the tumor cell surface, promotes tumor EMT, and prevents apoptosis through tumor cell upregulation of CXCR4." (PMID 40485724, 2025). "In addition, other studies have also confirmed that the increased expression of CXCR4 in HCC tissues is related to tumor size, metastasis, and patient survival." (PMID 40145607, 2025). "The CXCR4/SDF-1 axis exerts an important role in coordinating tumor cells and CAFs." (PMID 40626005, 2025). "Our data provide direct in vivo evidence that targeting CXCR4 itself is sufficient to suppress osteoclast activation and subsequent bone resorption, thereby extending previous work focused on the general biology of osteoclasts in the tumor microenvironment." (PMID 41413548, 2025). "These outcomes suggest that CXCR4-targeted therapies not only disrupt cancer cell migration and invasion but may also enhance immune-mediated tumor clearance, particularly in combination with immunotherapy." (PMID 41383468, 2025). "Flow cytometry results revealed that compared to the oe‐NC group, the number of T cells and B cells was significantly increased in the tumor tissues of mice in the oe‐NC+M2pep‐Cs NPs/Plerixafor group; while, in the oe‐CXCR4 group, the number of T cells and B cells was significantly decreased." (PMID 40536774, 2025). "Moreover, during the progression of HCC, increased matrix stiffness activates CXCR4 signaling, which in turn further accelerates tumor progression." (PMID 41301162, 2025). "The CXCL12/CXCR4 axis plays a significant role in tumour cell dormancy and metastasis in TNBC." (PMID 41002447, 2025). "This study included 90 patients and assessed CXCR4 expression in circulating tumor cells." (PMID 40607416, 2025). "Given the importance of axon-guided migration in GBM, we included inhibitors of Ephrin receptors (ALW-II-41–27 for EphA2, NVP-BHG712 for EphB4, and Ehp-inhibitor-1), and the CXCL12/CXCR4 axis (motixafortide), known to regulate directed migration in the hypoxic tumour core in immunotherapy." (PMID 41390851, 2025). "It is important to note that CXCR4-overexpressing cells (CXCR4+) are considered cancer stem cells (CSCs), due to their self-renewal and tumor-initiating capacity in mouse models of different cancer types, properties that differentiated cancer cells (CXCR4−) do not display." (PMID 40307933, 2025). "This suggests that low circulating CXCR4+ CD8+ T cells might lead to increased tumor infiltration by lymphocytes in response to CXCL12 signaling in tumor cells, creating a proinflammatory environment." (PMID 41149503, 2025).
tumor (continued). "Most importantly, preclinical studies suggest that the pharmacological inhibition of PARP not only affects DNA repair but also inhibits CXCL12/CXCR4 signalling, which influences tumour cell migration, reduces metastatic ability, and potentially increases therapeutic response." (PMID 41002447, 2025). "As such, the blockade of CXCR4 in combination with other radiosensitising approaches can be ideal to enhance treatment response and reduce relapse in TNBC by targeting tumour cells and reconstructing the protective microenvironment mediated by CXCR4/CXCL12 signalling." (PMID 41002447, 2025). "Therefore, CXCR4 is not only a marker of angiogenic vessels in TME but also functionally involved in tumor vascularization." (PMID 41210695, 2025). "Another experiment demonstrated that tumor-derived exosomes may enhance CXCR4 expression, potentially through the increased phosphorylation of NF-κB, leading to the expansion and migration of MDSCs." (PMID 40443670, 2025). "Inhibiting CXCR4 significantly reduced M2 macrophage accumulation and tumor invasion." (PMID 40756343, 2025). "The findings of the present study indicate that CAFs are involved in T cell recruitment through the CXCL12/CXCR4 axis, which may influence the efficacy of tumor immunotherapy." (PMID 40849508, 2025). "The CXCR4 blockade significantly suppressed primary tumor growth." (PMID 40756343, 2025). "Thus, CXCR4 inhibition, in conjunction with standard therapy, demonstrated promising potential for improved tumor control." (PMID 40427130, 2025). "Also, a role for nectin-4 has been demonstrated in promoting tumor-induced lymphangiogenesis and lymphatic metastasis in part through modulating the CXCR4/CXCL12-LYVE-1-axis." (PMID 40507273, 2025). "In addition, FGFR signaling regulates the chemokine system; for instance, it upregulates CXCR4 expression, thereby enhancing tumor cell chemotaxis toward CXCL12." (PMID 41514604, 2025). "However, both CD74 and CXCR4 were highly expressed in the infiltrating immune cells within the tumor tissues." (PMID 40018995, 2025). "By serving as a mediator of mechanical stimuli, CXCR4 may strengthen the interactions between MSCs and the tumor matrix, thereby promoting the enrichment of MSCs within HCC tissues." (PMID 41301162, 2025). "In this context, innovative nanomedical tools targeting the chemokine receptor CXCR4, show great promise in selectively eliminating receptor-overexpressing cancer cells, thereby limiting disease progression and tumor dissemination while minimizing side toxicities." (PMID 40307933, 2025). "Additionally, the CXCR4/CXCL12 axis has an important role in the remodelling of the tumour microenvironment (TME)." (PMID 41002447, 2025). "In addition, the activation of CXCR4 mediates protective effects for CSCs by maintaining a supportive niche that will provide physical shelter and immunity to therapeutic agents in the tumour microenvironment." (PMID 41002447, 2025). "CXCR4 showed high expression level in Epithelial Cell 1, Epithelial Cell 2, and parietal cells of the tumor group, revealing that CXCR4 may play a crucial role in the development of HP-positive STAD." (PMID 39886652, 2025). "CXCR4 is expressed by cancer cells and inflammatory cells in the tumor microenvironment (TME)." (PMID 40075611, 2025). "Similarly, we observed higher CXCR4 expression in purified M2 macrophages from peritumor tissues versus tumor tissues." (PMID 40756343, 2025). "Cxcr4 knockout in macrophages significantly inhibited primary tumor growth and invasion." (PMID 40756343, 2025). "These genetic events might be linked with positive regulatory loops or combined signalling hubs-such as the TGFβ-Wnt-CXCR4 circuits-that maintain tumor stemness, invasion, and immune escape." (PMID 41348904, 2025). "However, treatment with the Wnt inhibitor XAV939 (p = 0.0008) and the CXCR4 inhibitor AMD3100 (p = 0.0117) significantly reduced tumor weight in the CAF–PCSC co-implantation group." (PMID 40735647, 2025).
tumor (continued). "CTCE-DTX could self-assemble to NPs, targeting CXCR4-upregulated metastatic tumour cells and enhancing the DTX efficacy." (PMID 39231955, 2024). "Moreover, the murine model of the KrasG12V primary tumor had higher tumor cell survival and invasiveness, and C-X-C chemokine receptor 4 (CXCR4) overexpressed intravasated tumor emboli." (PMID 39056802, 2024). "Summarily, CD8, CD68, CD206, MIF, and CXCR4 expression are related with tumor progression." (PMID 39464891, 2024). "This derivative showed promising anti-tumor properties, inhibiting CXCR4 and tumor cell invasion." (PMID 39339093, 2024). "In a murine breast cancer model, tumor-draining lymph node-resident B cells, after being cultured ex vivo and then reinfused, could directly eradicate tumor cells via mechanisms involving CXCR4/CXCL12 and perforin." (PMID 39519376, 2024). "Tumor detection in solid cancers is more heterogeneous (as compared to [18F]-fluorodeoxyglucose ([18F]FDG)) with many entities showing only low to moderate in vivo CXCR4 expression." (PMID 39008062, 2024). "CXCR4 inhibitors can restrict tumor cell proliferation, migration, angiogenesis, and metastasis." (PMID 39001265, 2024). "Moreover, apigenin suppressed the expression of CXCR4 also in a xenograft mouse model, accompanied by the restriction of tumor growth." (PMID 39465008, 2024). "In our previous studies, we investigated whether serum CXCL12 and its specific receptor (CXCR4) levels may be used as potential biochemical tumor markers for OC." (PMID 38673838, 2024). "On the one hand systemic release of tumor-derived factors can downregulate CXCR4 resulting in the proliferation and mobilization of HSPCs like VEGFR1+ HSPCs, myeloid cell skewed LSKs and α-SMA+ cancer-associated fibroblasts activating Sca-1+c-Kit- cells to the premetastatic niche." (PMID 39148724, 2024). "The recruitment of GrB+ B cells to tumor tissues occurs through the MIF-(CD74 + CXCR4) axis." (PMID 38386050, 2024). "In addition, SHMT2 is involved in certain processes of tumorigenesis and development and is associated with the expression of MIF, CD74, CXCR4 and CD44 in the HNSCC tumor microenvironment." (PMID 38625586, 2024). "Similarly, 12G5 is an anti-CXCR4 antibody that has demonstrated anti-tumor and anti-metastatic activity in both endometrial cancer and osteosarcoma xenografted mouse models." (PMID 38612911, 2024). "This can attract CXCR4-positive tumor cells to specific metastatic sites." (PMID 38983932, 2024). "C-X-C chemokine receptor 4 (CXCR4) belongs to the seven-transmembrane G-protein-coupled receptors family and is closely involved in the epithelial-mesenchymal transition, invasion, angiogenesis, and maintenance of stemness of tumor cells." (PMID 39580422, 2024). "Additionally, we discovered that the high uptake of [18F]AlF-NOTA-QHY-04 in SCLC patients primarily depended on the high expression of CXCR4 in tumor cells, followed by macrophages and neutrophils in the tumor tissues." (PMID 39431004, 2024). "Similarly in prostate cancer, isolated CXCR4+ cells displayed a 3.8-fold increase in tumorigenicity, and tumor growth in vivo compared to CXCR4− cells." (PMID 38612911, 2024). "Furthermore, the interaction between fibroblast-derived CXCL12 and CXCR4 on tumor cells and monocytes also decreased notably following IGF2 loss." (PMID 39545420, 2024). "In addition, we investigate the CXCR4 expression and PD‐L1 expression of tumor tissues after different treatments." (PMID 38774946, 2024). "Additionally, C-X-C chemokine receptor type 4 (CXCR4) is activated in tumor cells under oxygen-deprived conditions." (PMID 38361941, 2024). "Of note, an ex-vivo sampling only displays tumor biology and receptor expression in the respective lesion, while assessment of the in-vivo CXCR4 expression offers a non-invasive whole-body evaluation, which reflects also possible intraindividual tumor heterogeneity." (PMID 38332341, 2024).
tumor (continued). "Consistently with the PET findings, high uptake of the tracer was observed in the A549/CXCR4 tumors, and the uptake can be significantly reduced via blocking with an excess of NOTA-QHY-04, which indicated again that the tumor accumulation of [18F]AlF-NOTA-QHY-04 was CXCR4 specific." (PMID 39431004, 2024). "CXCR4 is upregulated in malignant diseases and has a critical role in cell survival, proliferation, angiogenesis, metastasis, migration, recurrence, and resistance to chemoradiation, which lead to tumor progression and poor clinical outcome." (PMID 39001265, 2024). "MRI-guided biotherapy using anti-CXCR4-NaGdF4 NDs enables to suppress 46% tumor growth." (PMID 38982161, 2024). "Our study group has shown that CXCR4-targeted imaging using the radiopharmaceutical [68Ga]Ga-PentixaFor is an effective image tool in staging a variety of neoplasms, especially multiple myeloma, mantle cell lymphoma, small cell lung cancer, and adrenocortical neoplasms." (PMID 38332341, 2024). "Interestingly, IFN-β inhibits the infiltration of proangiogenic neutrophils that express VEGF, MMP-9, and CXCR4 and reduces tumor growth, suggesting a potential therapeutic approach for targeting neutrophil-mediated tumor angiogenesis." (PMID 38580870, 2024). "Exposure of MSCs to the pro-inflammatory cytokine TNF-α has been shown to upregulate CXCR4 expression, which may enhance the ability of MSCs to home to specific tissues, including tumours." (PMID 39062449, 2024). "In turn, the circFGFR1, which is significantly overexpressed in NSCLC tissues, acts as a tumor promoter by upregulating the C-X-C motif chemokine receptor 4 (CXCR4), a target gene for miR381-3p, and contributing to anti-PD-1 (Programmed cell Death Protein 1) resistance by sponging miR-381-3p." (PMID 38501058, 2024). "To investigate if factors in the tumor microenvironment mediate the MDMX-dependent upregulation of CXCR4, we explored if adding the stromal-derived extracellular signaling chemokine CXCL12 to cells grown in a culture would recapitulate the results observed in the xenograft tumors." (PMID 39766093, 2024). "Thus, the MIF/CXCR4 signaling axis between tumor cells and macrophages was selected for further investigation." (PMID 39464891, 2024). "Similarly, patients with a pCR were less likely to express CCR5, CCR7, CXCR4, and CXCR5 on tumors, and CXCR4 high expression (≥20%) on TILs in core biopsy tumor materials." (PMID 39001456, 2024). "The CXCR4/CXCL12 complex mediates tumor growth and metastasis." (PMID 38893721, 2024). "Due to proven upregulation in an ex-vivo setting, CXCR4-targeted [68Ga]Ga-PentixaFor PET/CT has entered the clinical arena for assessing sites of disease in patients with varying neoplasms, including hematological malignancies, solid tumors or benign pathologies." (PMID 38896128, 2024). "Furthermore, IL-6, CXCR4, CXCL8, and MMP-9 indicate higher diagnostic utility based on the area under the ROC curve (AUC) than well-established OC tumor markers, whereas CLDN18.2 can be used in novel targeted therapies for OC patients." (PMID 38673838, 2024). "The MIF/CXCR4 axis is the most ligand–receptor interaction between macrophages and tumor cells." (PMID 39464891, 2024). "As such, the AMD3100 inhibitor (which blocks CXCR4) may work well to block primary tumor cells from intravasation into the blood stream." (PMID 39766093, 2024). "Notably, VUF, exogenous CXCL12hi, CXCR7 knockdown, or CXCR7 overexpression had a minimal and inconsistent impacts on tumor cell and CXCR4 expression." (PMID 38898023, 2024). "Blocking CXCR4 impaired the anti‐tumor effect of CXCL12 in a mouse model." (PMID 39422063, 2024). "Moreover, the blockade of CXCR4 alleviates tumor desmoplasia and increases T-cell infiltration in metastatic breast cancer." (PMID 38182756, 2024).